SOX2 (SRY-box transcription factor 2)
Diseases named in the same sentence as SOX2 in open-access papers (continued):
Sharing a sentence is not in itself a finding about the gene and the disease.
tumor (continued). "Because the cell growth rate was suppressed in vitro by SOX2 KO, we measured tumorigenic activity for an extended period; however, we did not detect tumour formation up to 13 weeks after injection." (PMID 35190631, 2022). "In detail, male sex, T3 and T4 stage, moderate and poor differentiation, tumor ≥ 2 cm, Ki67 ≥ 15%, SOX-2 negative expression, middle lobe lesion and adenocarcinoma were relative risk factors affecting SMARCA2-negative expression (P < 0.05)." (PMID 35289322, 2022). "Interestingly, we observed a significant overexpression of OCT4, SOX2, and NESTIN in both tumor KDM5C subgroups compared to the control samples." (PMID 36142158, 2022). "In contrast, 96 h-SPS, but not RPMI, supported the Oct4 and Sox2 genes expression in vitro, whereas these supports were lost in the tumor’s microenvironment." (PMID 36908807, 2022). "SOX2 expression was an intrinsic characteristic of any single tumor and did not change following recurrence or progression." (PMID 36232992, 2022). "Tumours from HCT116‐KOs cells did not present any statistically significant change in SOX2 expression, but they shared a significant reduction in KLF4 expression." (PMID 34623757, 2022). "Notably, we found that YTHDC1 mRNA expression levels were significantly and positively correlated with those of BMI1 and SOX2, which are HNSCC tumor stem cell-specific indicators." (PMID 36411870, 2022). "In NSCLC, male sex, T3 and T4 stage, moderate and poor differentiation, tumor ≥ 2 cm, Ki67 ≥ 15%, SOX-2 negative expression, middle lobe lesion and adenocarcinoma were relative risk factors affecting SMARCA2-negative expression." (PMID 35289322, 2022). "In addition, areas of tumor cell foci showed extensive Ki-67 expression, strong CD31 staining demonstrated that the tumor was highly angiogenic, and displayed GBM tumor stem cell positive markers such as SOX2 and GFAP." (PMID 36506083, 2022). "While changes in mouse diet did not appreciably effect tumor growth, the high-fat diet potentiated SOX2 expression and the downstream lineage plasticity of the tumors." (PMID 35884514, 2022). "Moreover, targetable signalling events observed in in vitro models of HNSCC were also connected with downregulation of Oct4, Sox2, nestin, and CD44 expression, as well as inhibited tumour sphere formation." (PMID 35276890, 2022). "The mRNA expression of tumor stem cell markers (CD133, SOX2 and OCT4) in the CRC xenograft tissues of mice was then found to be up-regulated in the presence of β-catenin overexpression alone, and the up-regulation was reversed when β-catenin overexpression was combined with FOXQ1 knockdown." (PMID 35183223, 2022). "Moreover, we compared the expression of each TCFL5 exon with that of SOX2 and KLF4 in tumour samples." (PMID 34623757, 2022). "Our results are consistent with these studies identifying ZFP36L1 as a tumor suppressor in SCLC, where it also possesses the ability to bind and downregulate mRNAs that promote SCLC neuroendocrine differentiation including INSM1 and SOX2." (PMID 36008402, 2022). "The overexpression of Oct4 and c-Myc in tumor cells reduced the expression of downstream oncogenic genes in parental tumor cells but the overexpression of Sox2 and Klf4 did not." (PMID 35547745, 2022). "Using scRNAseq data from patient samples of primary and recurrent GBM (GSE154975), we identified multiple cell types based on markers from the original study: macrophages (ITGAM), T cells (CD3E), Tregs (CD4, CD3E, FOXP3), low-reads/dying cells (MALAT1), and tumor/normal brain cells (GFAP, SOX2)." (PMID 36591276, 2022). "Positive correlation of TCFL5 and SOX2 was found in the normal region adjacent to the tumour samples but not in healthy tissue or tumour samples, while KLF4 negatively correlated with TCFL5 in tumour samples." (PMID 34623757, 2022).
tumor (continued). "A similar trend was seen for cases with high tumor FMOD and SOX2 expression (p = 0.09)." (PMID 35737114, 2022). "Next, IHC was used to examine the expression of SOX2, cGAS, STING, ki67, CD3 and CD8 in tumours." (PMID 35415876, 2022). "We exhibited that the Ki-67+ and SOX2+ cells belonged to a different population of tumor cells, and SOX2+ cells were almost negative for Ki-67." (PMID 35055392, 2022). "Inhibition with PFK158 or genetic knockdown of PFKFB3 showed reduced tumor formation in the CSC xenograft model with reduced expression of phospho-PFKFB3 S461 and total PFKFB3, and cancer stem cell markers including CD133, CD44, Aldh1, Sox2, and ABCG2." (PMID 35804016, 2022). "In a second set of GBM tumor samples (n = 16, samples frozen at −80 °C), we used immunofluorescence to study the expression of SOX2 in larger regions of tumor tissue (rather than the cores of the TMA)." (PMID 36333778, 2022). "We presented in this study that two of the Yamanaka factors, Oct4 and c-Myc, can be used to convert the secretome of tumor cells into tumor-suppressive, while two other factors, Sox2 and Klf4, failed to induce tumor-suppressing capabilities." (PMID 35547745, 2022). "Although LY2228820 only slightly inhibited tumor growth rate, it markedly inhibited paclitaxel-induced increases of ALDH+ and mammosphere-forming cells and of expression of Nanog, Sox2, and Klf4." (PMID 35401817, 2022). "For the metastatic Detroit 562 cell line, the least supportive CAFs were those derived from the CL mRNA subtype of HNSCC tumour mass characteristic by αSMA-low, elevated levels of oxidative stress response genes, including NFE2L2 and SOX2, and a history of heavy smoking." (PMID 35565415, 2022). "In addition, Ki67, SOX2 and N‐cadherin were significantly downregulated in the PCAT1‐depleted tumours, while cGAS, STING and E‐cadherin were upregulated." (PMID 35415876, 2022). "Interestingly, tumor sphere and self-renewal markers, such as CD133 and SOX2, were significantly reduced at the protein level after treatment with DHCT compared to nicotine only treated group cells." (PMID 35111269, 2022). "Further characterisation by matched single cell RNA-sequencing of the same tumours revealed that BCL-xL and MCL-1 expression correlated with expression of neural stem cell markers NES, SOX2 and SOX9 and the degree of malignancy within the tumours (CNA gain chromosome 7), independently of cell cycle." (PMID 35473984, 2022). "The remainder of the tumor mass was isolated either for qRT-PCR experiments to verify LPCAT1 expression, or for western blot analysis experiments to verify LPCAT1, Smad, p-Smad, ki-67, and SOX2 expressions." (PMID 35880567, 2022). "Sox2 emerged as a gene that is ectopically expressed in murine cSCC tumor initiating cells (TICs) but not in other progenitor cells of the skin." (PMID 35892887, 2022). "We observed that histone demethylase, Kdm3a, was downregulated in tumor cells treated with Oct4 CM and c-Myc CM, but it was not altered by the treatment with Sox2 CM and Klf4 CM." (PMID 35547745, 2022). "Inhibition of UPF1 may be used to lower the chances of CSCs being the tumor origin and may be beneficial for chemoprevention while sparing normal endometrial stem cells via the LINC00963/miR-508-5p/SOX2 pathway." (PMID 35318304, 2022). "Given the critical role of SOX2 in GSC self-renewal and tumor formation, we hypothesized that WWP2 knockdown might promote these GSC phenotypes." (PMID 34732716, 2021). "Concerning a correlation with disease characteristics, an association of high expression of ALDH1 with grading, high expression of CD44 with localization of the neoplasm, T- and N-category, and UICC stage, as well as high expression of SOX2 with perineural invasion was observed." (PMID 33009929, 2021).
tumor (continued). "Additionally, sh-SOX2 treatment decreased mRNA expression of SOX2, CCAT1, EGFR, and miR-222-5p in tumor isolated from nude mice, but increased the mRNA expression of CYLD." (PMID 33952719, 2021). "Moreover, Sox2 is related to tumour initiation, therefore an excessive expression of CDK1 promotes the development of CSCs in the tumour microenvironment by Sox2 activity." (PMID 34503199, 2021). "Moreover, we demonstrated that silencing UCA1 or up-regulating miR-122-5p would reduce SOX2 expression and depress the invasion, proliferation, migration, boost apoptosis of CD133+CaSki cells as well as suppress the tumor weight and volume in nude mice." (PMID 34053467, 2021). "Prrx1 potentiated stemness acquisition in non-stem tumor cells (NSTCs) and stemness maintenance in GSCs, accompanied with increased expression of stemness markers such as SOX2." (PMID 34131109, 2021). "Cells with enhanced tumor-initiation capacity and resistance to chemotherapy in vitro have significantly enriched SOX2, but not OCT4 or NANOG." (PMID 33445692, 2021). "Analysis of cells treated with AZD4573 showed that the levels of Sox2 and Sox9 are reduced, implying that inhibiting CDK9 might prevent their tumor promoting functions." (PMID 34359807, 2021). "In addition, expression of Sox2/SOX2 and Il20ra/IL20RA was enriched in the sorted SP and/or tumor spheres of EO771FL and T-47D cells." (PMID 33456560, 2021). "Apoptosis of the Sox2+ve pituitary stem cells coupled with cell growth arrest leads to depletion of the stem cell pool and pituitary hypoplasia, rather than tumour formation." (PMID 33795686, 2021). "In addition, SOX2 and OCT4 expression is positively related to tumor aggressiveness in breast cancer." (PMID 35008527, 2021). "In the process of tumor cell dormancy, DTCs may retain stem-like properties such as quiescence, with the increased expression of stem cell markers CD44, SOX2, CD133, or Lgr528,29." (PMID 33986252, 2021). "Many of the tumor oncogenic effects were fulfilled through the MYC and/or SOX2." (PMID 34898574, 2021). "Moreover, CDK1 knockdown decreased the phosphorylation, transcription activity, and nuclear distribution of SOX2, while knockout of SOX2 significantly reduced CDK1 overexpression-induced tumor-initiating capacity." (PMID 34621737, 2021). "SOX2 expression levels within tumor tissues were observed and classified as negative, weak, moderate, or strong staining." (PMID 33789601, 2021). "The aim of this study is to explore SOX2 and AGR2 biomarkers expression in tumor tissue of ER-positive breast cancer patients in combination with evaluation of serum AGR2 level of these patients in order to validate these biomarkers as early predictors of tamoxifen resistance." (PMID 34567804, 2021). "Our GBM orthotopic xenografts also confirmed that SON reduction in GSCs leads to depletion of PTBP1 as well as the well-known GBM stemness marker SOX2, suggesting targeting SON efficiently suppresses the tumorigenic ability of GSCs and inhibits tumor cells’ stemness in vivo." (PMID 34548489, 2021). "Tumor samples of 40 consecutive patients with adenocarcinoma of the major salivary gland treated with curative intend at one tertiary center were stained with the CSCs ALDH1, BMI-1, CD44, Nanog, and SOX2." (PMID 33009929, 2021). "Moreover, the tumor cells lining VM channels were found to express the stem cell factor SOX2 and OCT4 in hepatocellular carcinoma, suggesting a new mechanism for CSC-mediated tumor VM formation." (PMID 33946480, 2021). "Additionally, correlations between Tregs and CTLs infiltration and the expression of tumor PD-L1 and various well-established CSCs markers (i.e. NANOG, SOX2, OCT4, Nestin and PDPN) are also assessed." (PMID 34201050, 2021). "Furthermore, increases in the properties of stem cells were measured by assessing the capacity for tumor formation and performing transcriptional analysis of the OSKM genes (OCT4, SOX2, KLF4 and MYC), NANOG, NES and PROM1." (PMID 34364391, 2021).
tumor (continued). "The aim of this work is to explore SOX2 and AGR2 biomarker expression in the tumor tissue of ER-positive breast cancer patients in combination with the evaluation of serum AGR2 level of these patients in order to validate these biomarkers as early predictors of tamoxifen resistance." (PMID 34567804, 2021). "Type A cultures form tumor spheres, grow as intracranial xenografts and express astroglial and stem cell-related genes including GFAP (Glial Fibrillary Acidic Protein), SOX2 (SRY (sex determining region Y)-box 2) and PDGFRA (Platelet Derived Growth Factor Receptor α)." (PMID 34021259, 2021). "For the castration-induced regression nadir group (i.e., those with the weakest or most unsuccessful castration-induced tumor regression), GSE1, CYP3A5, CTNNB1, CYP3A4, POU5F1, ABCB1, alkaline phosphatase liver/bone/kidney isozyme (ALPL), PROM1/CD133, ABCG2, and SOX2 were concomitantly upregulated." (PMID 34439112, 2021). "Limiting dilution in in vivo experiments implicated SOX2, but not OCT4 or NANOG, with early tumor-initiation." (PMID 33445692, 2021). "Given the deficit of reliable biomarkers for NSCLC CSCs, we obtained potential CSC subpopulations from NSCLC cell lines based on general traits of CSCs, including tumor sphere-forming capacities 45, expression of CSC markers, such as Oct4, Nanog, and Sox2 46, and ALDH activity." (PMID 33456581, 2021). "Material from the regrown tumor was collected to establish an isogenic model of carboplatin-resistant TNBC (C4O) and gene expression analysis revealed changes in Wnt signaling target AXIN2 and pluripotency and stem markers NANOG, OCT4, SOX2, and LGR5." (PMID 34367990, 2021). "Genetic tracing has been initially carried out in the inducible model to reveal that the ACP-like tumours do not derive from SOX2 + pituitary stem cells expressing oncogenic β-catenin." (PMID 34019103, 2021). "Since circFat1 KD attenuated STAT3 activation and SOX2 expression, we further examined whether circFat1 KD could enhance PD1 blockade‐mediated immunotherapy of HNSCC by activating tumor cell intrinsic type 1 IFN signaling." (PMID 34258151, 2021). "In addition, the ability of 786-O cells to generate tumor spheres was enhanced and the protein expression of CD133, Bmi-1, SOX-2 were upregulated under the culture with ox-LDL." (PMID 33935779, 2021). "However, to better reconstitute the heterogeneity of GBM tissue and the tumour microenvironment we would propose to develop cancer cell lines that are BTK+/SOX2+ and BTK−/SOX2+, along with BTK+/CD163+ and BTK−/CD163+ immune cell populations." (PMID 34645618, 2021). "Future studies should explore the relations among SOX2, the IFN/IDO1 cascade, and tumour dormancy." (PMID 34539663, 2021). "Instead, targeted SOX2 + stem cells give rise to β-catenin-accumulating cell clusters, while the tumours originate from a different cell lineage as they do not express the lineage reporter, nor do they contain a Ctnnb1 exon 3 deletion." (PMID 34019103, 2021). "Thus, these two examples demonstrate a striking heterogeneous and inverse expression between SOX2 and BTK proteins in the same tumour." (PMID 34645618, 2021). "Furthermore, when endogenous ELK-1 was silenced in the primary tumor culture of patient 624 (middle level of ELK-1 expression), CD133, NANOG, SOX2, and POU5F1 levels were all downregulated as compared to scramble RNA control." (PMID 33672811, 2021). "The aim of this study to explore SOX2 and AGR2 biomarkers expression in tumor tissue of ER-positive breast cancer patients in combination with estimation of serum AGR2 level of these patients in order to validate these biomarkers in the early prediction of tamoxifen resistance." (PMID 34567804, 2021). "These outcomes manifested that RP11-499E18.1 overexpression might carry out its tumor-suppressing efficacy through decreasing the interaction between PAK2 and SOX2, and thereby lessen the nuclear translocation of SOX2." (PMID 34621737, 2021).
tumor (continued). "More significantly, collagen/fibronectin could facilitate the activation of PI3K/AKT/SOX2 and CDC42/YAP-1/NUPR1/Nestin signaling pathways via integrin αvβ3, eliciting sustained tumor growth and cancer relapse." (PMID 33408794, 2021). "In the case of CAA, the proliferating cells were distributed randomly in the middle areas of the tumorous epithelium; thus, the expression of SOX2 and Ki-67 was not colocalized in this tumor." (PMID 34072517, 2021). "In addition, SOX2 has been shown to activate the JAK-STAT pathway, which regulates both immune response and tumor progression, while inhibiting SOCS3 and PTPN1, which are regulators of immune signaling." (PMID 34831420, 2021). "Surprisingly, the expression of SOX2 was more detected in normal samples and most tumor tissue samples had less SOX2 expressed than in adjacent normal tissue." (PMID 33471801, 2021). "We reveal that the combination of Rova-T and CBL decreases SOX2 and attenuates the in vivo self-renewal capability of SCLC tumours by eradicating TICs, and thereby may also help to counteract relapse." (PMID 33257843, 2021). "In addition, we observed that silencing WDR12 in tumors remarkably decreased tumor cell proliferation and GSC population, as assessed by Ki67 and SOX2 staining respectively." (PMID 34868955, 2021). "Activated p38γ can mediate the ubiquitination and degradation of stem cell proteins such as Sox2, Oct4 and Nanog by means of activating the downstream kinase MK2 to phosphorylate Hsp27, thereby inhibiting the tumor stem cell characteristics and tumor initiation ability of NSCLC cells." (PMID 34671218, 2021). "As one of the four factors (SOX2, C-Myc, OCT-4, and KLF4) required for reprogramming adult fibroblasts and skin melanocytes into induced pluripotent stem cells (iPS), KLF4 plays an essential role in tumor initiation and cancer stemness." (PMID 33726845, 2021). "CD133+ CRC cells manifested the CSC-like properties, such as higher levels of SC markers OCT4 and SOX2, tumor sphere forming ability, and more tumorigenic in NOD/SCID mice, which is consistent with OCT4 and SOX2 overexpression in poorly differentiated human tumors." (PMID 33562604, 2021). "In addition, we found that the expression of stemness genes was upregulated in the soft tumor cells (Nestin, OCT3/4 and SOX2 for 4T1/MCF‐7; Nanog, OCT3/4, SOX2, and CD133 for B16F1/MP‐1), while the BCL9L knockout reversed this effect (Fig EV5G)." (PMID 33274785, 2021). "In this study, they noted that SOX2 was not present in normal skin but was clearly expressed at an early stage in tumor formation." (PMID 33613850, 2021). "As FOXM1 is an oncogenic regulator that promotes GSC proliferation and expression of the stem cell marker SOX2, and SATB2 regulates FOXM1 expression, we next explored whether FOXM1 mediates the effects of SATB2 on GSC proliferation and tumor growth." (PMID 33124191, 2020). "Furthermore, SOX2 is responsible for maintaining the CSC properties, resulting in aggressive tumor growth, invasion, and resistance to conventional therapy in various cancers." (PMID 32144236, 2020). "All tumours showed cells with enlarged, pleomorphic and occasional hyperchromatic nuclei on H&E, whilst all conditions show diffuse staining for GFAP (cytoplasmic) and SOX2 (nuclear), with a smaller fraction positive for OLIG2." (PMID 31988455, 2020). "Isolated GSCs were characterized by the expression of the GSC markers (SOX2, OLIG2, CD133, L1CAM) and functional assays including serial neurosphere formation assay, in vitro cell differentiation assay and in vivo limiting dilution tumor formation assay." (PMID 32541784, 2020). "One population within the tumor niche had the markers SOX2+/NANOG+/KLF4+/c-MYC+/OCT4−, and two populations in the peritumoral stroma had the markers SOX2+/NANOG+/KLF4+/c-MYC+/OCT4− and SOX2+/NANOG+/KLF4+/c-MYC+/OCT4+." (PMID 32974184, 2020).